IFNG (interferon gamma)
Diseases named in the same sentence as IFNG in open-access papers (continued):
Sharing a sentence is not in itself a finding about the gene and the disease.
tumor (continued). "Lastly, the impact of IFNγ signaling on targets other than tumor cells, for example, endogenous immune cells, likely also contributes to discrepancies between the in vitro and immunodeficient settings compared to immunocompetent settings." (PMID 38052854, 2023). "The growth of tumours derived from IFNγ-naïve CT26 cells that regrew following α-PD-1 administration was also suppressed by PARP14i treatment." (PMID 37752135, 2023). "Upon activation of stimulatory receptors, NK cells express inflammatory cytokines such as interferon gamma (IFN-γ) and perforins, activating the apoptotic pathway in tumor cells." (PMID 38139779, 2023). "In vitro experiments, we investigated the expression levels of ARL4C in four tumor cell lines treated with various cytokines, namely IFNβ, IFNγ, TGFβ, and TNFα." (PMID 38178862, 2023). "In the BRCA1(−) tumor model, CTLA4 blockades combined with PARPi induce protective anti-tumor immunity and significant survival benefit by locally inducing anti-tumor immunity and increasing levels of IFNγ." (PMID 36900418, 2023). "A total of 11 immunotherapy markers, namely, TIDE, interferon gamma (IFNG), microsatellite instability (MSI), Merck18, cluster of differentiation (CD) 274, CD8, dysfunction, exclusion, MDSC, CAF, and tumor-associated macrophages M2 (TAMM2), were evaluated." (PMID 38021786, 2023). "M1 macrophages are activated by Th1 cytokine interferon-gamma (IFN-γ) or lipopolysaccharides (LPS) and have an anti-tumor effect through complement-mediated phagocytosis of tumor cells." (PMID 37720221, 2023). "IFNγ is produced by tumor-specific T cells and performs an effective anti-tumor immune response by recognizing corresponding receptors on cancer cells or antigen-presenting cells." (PMID 36875059, 2023). "Cytotoxic T lymphocytes (CTLs) control tumors via lysis of antigen-presenting targets or through secretion of cytokines such as interferon-γ (IFNG), which inhibit tumor cell proliferation." (PMID 37182110, 2023). "CD8+ T cells in the tumor microenvironment are capable of producing interferon-γ (IFNγ), which stimulates the upregulation of PD-1/PD-L1 and IDO1 gene expression." (PMID 37153654, 2023). "Conversely, in vitro CAR-T efficacy appears to be at least partially dependent on the ability of tumor cells to sense IFNγ." (PMID 38052854, 2023). "Proper application of anti-IFNγ increased Cpt-DNA adducts in tumour tissues, indicating the promotion of drug delivery." (PMID 37056922, 2023). "Low-dose RT-mediated increased tumor PD L1 expression via the IFNγ signaling peaking at 72 h can be achieved through the concomitant use of anti-PD-1 or anti-PD-L1." (PMID 38276666, 2023). "The tumor-suppressing capability of the GPR15-GPR15L axis was associated with a significant influx of CD4+ and CD8+ T cells into the tumor, in particular IFNγ or TNFα secreting T cells." (PMID 38074634, 2023). "As a key component of inflammatory signalling that characterises the TME, the cytokine interferon γ (IFNγ) exerts divergent effects on tumour immune responses, including those elicited by ICBT." (PMID 37752135, 2023). "In the tumour microenvironment, sources of IFNγ include tumour-infiltrating NK cells, ILC1s, γδ T cells, CD8+ T cells, and Th1 cells." (PMID 37455828, 2023). "Next, the proportion of IFNγ+CD8+ T cells in a tumor was investigated to accurately assess the strength of antitumor immunity." (PMID 37217527, 2023). "In humans, an IFNγ-induced signature, including CXCL9/CXCL13 expression, was associated with a favorable response to ICB in multiple tumor types." (PMID 37492581, 2023). "However, since PD-L1 tumor expression is mainly modulated by IFNG, and since in the present study the higher IFNG-induced risk of death was exclusively observed in the PC cohort with high tumor PD-L1 expression, we cannot rule out that the value of this might be biased." (PMID 36980174, 2023).
tumor (continued). "In a lung metastasis model, YB1-induced IFNγ expression was found to be responsible for its anti-tumor effect." (PMID 38020179, 2023). "Gangliosides appear to have the ability to inhibit the LPS-driven and IFNγ boosted DC maturation and cytokine production, and therefore downregulate the pro-inflammatory response triggered against tumor cells." (PMID 37266839, 2023). "Ensuing IFNγ signaling transforms myeloid, stromal, and tumor niches to yield an immune-supportive ecosystem." (PMID 37543621, 2023). "Increased Treg numbers and Treg/CD8+ T cells ratios and lower IFNγ-producing CD4+ T cell numbers indicated an immunosuppressive tumor environment in cSCC from SOTRs." (PMID 37887285, 2023). "As a proxy for IFNG levels inside the tumor, we used mRNA expression data recorded within the same experiments as the previously analyzed image and volume progression data." (PMID 37182110, 2023). "IFNG, AC006369.1, and CCR7 were closely linked with the tumor microenvironment components (e.g., macrophages, CD4/CD8 T cells, NK cells), and immune checkpoints (notably PD1/PD-L1)." (PMID 37408777, 2023). "Activated (CD8+ IFNγ+) cytotoxic T cells (CTLs) were detected in the tumor upon treatment with mIL12-FHAB-hIL15 at a 2.5-fold increase compared with the control." (PMID 38250068, 2023). "Then, Dox was withdrawn for 48 h to stop cytokine production, and tumor tissues were analyzed for colocalization between IFNγ–GFP and HS." (PMID 36732425, 2023). "Building on our in vitro findings that IL-12-induced IFNγ signaling is critical for CAR T-cell anti-tumor activity, we next engineered synthetic IL-12 into our TAG72-CAR T cells." (PMID 37550294, 2023). "FAs reduce mTORC1/c-MY signaling in NKs and the rates of glycolysis and OXPHOS, which results in the low production of interferon gamma (IFN-γ), granzyme B and perforin and reduced cytotoxicity to targeted tumor cells." (PMID 36765683, 2023). "For example, PD-L1 expression in tumor cells is induced by IFN-γ, and IFNγ signaling is dependent on sphingolipid metabolism." (PMID 38069222, 2023). "IFNg, secreted by the immune microenvironment in tumours in situ, induces tumour cell dedifferentiation and ferroptotic cell death in melanoma." (PMID 37236926, 2023). "Neutralising IFNγ combined with cisplatin reduced tumour volume and tumour weight to a greater degree compared than that reduced by cisplatin alone." (PMID 37056922, 2023). "Overall, these data suggest that, in our in vitro screen setting, tumor cell death predominantly results from high dose IFNγ released from CAR-T cells following mCD19/anti-mCD19 CAR-T interaction." (PMID 38052854, 2023). "The IFNγ protein has dual anti- and pro-tumor roles as it has cytotoxic effects on tumor cells through IFNγ receptor and yet induces expression of pro-tumor, immune suppressive checkpoints such as PD-L128." (PMID 37106127, 2023). "T cells have some anti-tumor activity, particularly Th1 cells that produce interferon gamma (IFN-γ)." (PMID 38258066, 2023). "Taken together, these results show that ILKAP deletion enhances tumor killing independently of increasing sensitivity to IFNγ or TNF." (PMID 37732732, 2023). "The interferon-gamma cascade plays a role in the effector immune response, which aids in the elimination of tumor cells through the activation of apoptosis." (PMID 37111629, 2023). "IFNγ produced by immunotherapy-activated CD8+ T cells can promote tumor ferroptosis and induce radiosensitization." (PMID 37714846, 2023). "Following establishment of tumours derived from IFNγ-naïve YUMM2.1 and MC38 cells, mice were treated with two doses (spaced three days apart) of IgG2a or α-PD-1 antibodies." (PMID 37752135, 2023). "As signaling of IFNγ in the tumor cells was found to be dispensable for equilibrium, we next sought to determine which host cells were responding." (PMID 36881506, 2023).
tumor (continued). "Flow cytometry analysis of MHC-I expression showed a greater proportion of CD45- cells (including tumour cells) positive for expression of MHC-I in both FAK-wt and FAK-/- tumours in response to IFNγ treatment." (PMID 36977556, 2023). "Inhibiting IL-13 has many theoretical benefits, including reducing MDSCs and M2 TAMs, while promoting anti-tumour IFNγ+ and T cell infiltration." (PMID 37455828, 2023). "Analysis of tetramer+ TILs from triple-treated mice in both tumor models showed that the percentage of polyfunctional (IFNγ+TNF+) cells decreased from the TCF1+TIM3-PD1+ to the CD101-TCF1-TIM3+PD1+ to the CD101+TCF1-TIM3+PD1+ subset." (PMID 37045833, 2023). "ILC1s are defined by the master transcription factor T-bet and are activated by the presence of IL-12, IL-15, and IL-18 to mount an anti-viral and anti-tumor response by producing effector cytokines IFNγ and TNF-α." (PMID 38567059, 2023). "Interferon-gamma (IFN-γ), the sole member of the type-II interferon family, is well known to protect the host from infectious diseases as well as mount anti-tumor responses." (PMID 37965321, 2023). "Peroxidation of unsaturated fatty acids induces ferroptosis-mediated anticancer immune effects, and IFNγ released from CD8+ T cells induces lipid peroxidation in tumor cells and promotes tumor regression." (PMID 39872623, 2023). "The cytokines, primarily IFNγ, contain angiostatic properties and block the formation of blood vessels around the tumor, leading to the death of tumor cells." (PMID 36946842, 2023). "Quantitation of tumor tracer uptake illustrated a significant increase in IFNγ tracer accumulation in tumors from ICI-treated (25.23 ± 6.48 %ID/mL) versus untreated mice (16.22 ± 2.68 %ID/mL, p<0.00055)." (PMID 38130991, 2023). "In TLN, Caprin-1 suppressed activation of lymphocytes, T cell activation and anti-tumor cytokine and chemokine (IFNG, IL1B, IL21 and TNF) production." (PMID 38082307, 2023). "Note that this small difference in sensed IFNγ by tumor cells between the homogeneous and heterogeneous scenario does not occur for tumors without IFNγ inhibition or with TGFβ-mediated IFNγ inhibition." (PMID 37638024, 2023). "The results revealed significant disparities in ARL4C expression within the IFNβ and IFNγ-treated tumor cell lines." (PMID 38178862, 2023). "In general, cytokines involved in type 1 immunity including IFNγ, IL-12, and TNFα are shown to orchestrate anti-tumour immune responses against a broad range of cancer types in numerous preclinical and clinical studies." (PMID 37455828, 2023). "Most CC cell lines exhibit low PD-L1 expression, which requires IFNγ stimulation; considering tumor heterogeneity, it is also important to consider cells with endogenous PD-L1 expression." (PMID 37316937, 2023). "The sensing by DCs of IFNγ produced by tumor-infiltrating T cells is critical to the response to anti-PD-1." (PMID 37565053, 2023). "The combination of anti-PD-1 with FOLFOX in this study was associated with IFNγ-producing CD8+ T cells and increased expression of PD-L1 on tumor cells, suggesting a link between FOLFOX-mediated antitumor response and the PD-1/PD-L1 pathway." (PMID 36039609, 2023). "Murine tumor cells displayed significantly higher NOS2 activity in response to IFNγ or LPS, suggesting a key distinction between tumor cells and macrophages." (PMID 37169743, 2023). "Using an in vivo genomewide screen in a model of B cell leukemia, we identify an unexpected mechanism of CAR-T resistance in which interferon gamma from the in vivo tumor microenvironment induces an adaptive T-cell resistance program in tumor cells." (PMID 38052854, 2023). "We used this model to quantify the contribution of IFNG and cytotoxicity to the anti-tumor activity of CTLs, which led to the conclusion that IFNG contributes most to tumor growth blockade by CTLs." (PMID 37182110, 2023).
tumor (continued). "The strong antibody response in this patient, together with their cellular responses, reflected by high Th1 cytokine (IFNγ/IL-10, and TNFα/IL-10) ratios, correlated with the patient’s increase in progression-free survival and tumor reduction." (PMID 38203458, 2023). "Since both extremes are likely relevant and can depend on tumor-secreted factors such as galectins, we investigated two extreme spreading scenarios by modifying the rate of cellular uptake of IFNγ." (PMID 37638024, 2023). "One study showed that low dose of IFNγ endowed tumor stemness in TME of NSCLC via regulation of ICAM1/PI3K/AKT/Notch-1 pathway, whereas high dose of IFNγ induced apoptosis of NSCLC cells via activation of JAK1/STAT1/caspase pathway." (PMID 37033636, 2023). "The authors also found that changes in the immune microenvironment, including differences in the proportion of tumor-specific T cells and their ability to produce interferon gamma (IFNγ), influence operative timing." (PMID 36761954, 2023). "Considering the low expression of PD-L1 in most CC cell lines, we decided to induce PD-L1 expression with IFNγ treatment, as IFNγ upregulates PD-L1 expression in tumor cells." (PMID 37316937, 2023). "IFNγ signaling strongly induces PD-L1 expression on tumor cells through IRF1-mediated transcriptional activation of the PD-L1 gene." (PMID 37024504, 2023). "IFNγ blockade abrogates tumor control by anti-PD-1 and alongside the resulting DC-produced IL12, underlies effective immune checkpoint blockade." (PMID 37565053, 2023). "Upon activation, the T cells release interferon-gamma (IFN-γ), which promotes cytotoxicity and results in the upregulation of PD-L1 expression in the tumor cells." (PMID 37842239, 2023). "Assessment of peripheral cytokines in both MC38 and EMT6 tumor models revealed that the combination treatment with docetaxel + NHS-IL-12 yielded increased levels of the proinflammatory cytokines IFNγ, IL-12, and tumor necrosis factor α (TNFα)." (PMID 37166485, 2023). "A similar result was observed when examined LN samples, suggesting that IFNγ affected cell type proportions mainly at the tumor site." (PMID 36658158, 2023). "Among the anti-tumor effects, IFNG can aid in the recruitment of innate immune effectors, kill tumor cells, or exert antiproliferative effects on tumor cells." (PMID 37182110, 2023). "Treating with αPD-1 led to increased IFNγ production by all T cells in the tumor and increased responses when combined with VVdnTGFβmm." (PMID 37552475, 2023). "STAT4 plays a critical role in IL12 response and functions in the development of the Th1 and Th2 lymphocytes, and interferon gamma signaling in response to the stimulation of cytokines, which is important in the modulation of tumor immunity." (PMID 37393410, 2023). "The seYTS cells injected i.v. were able to interact with the tumors and to inhibit tumor growth presumably via IFNγ secretion." (PMID 37609636, 2023). "MDSCs also interact with tumor macrophages and dendritic cells to influence their activity and upregulate the activity of Tregs through their production of IL-10, TGFβ, IFNγ, and CD40–CD40L interactions." (PMID 37376141, 2023). "Other biomarkers, such as the tumour mutational burden (TMB), interferon-gamma signatures and tumour-infiltrating lymphocytes (TILS), among others, are biologically plausible but have yet to show a conclusive correlation with clinical outcomes." (PMID 37511609, 2023). "In the current study, we further validated the utility of our IFNγ immunoPET tracer to detect anti-tumor immunity in situ using a pre-clinical model that is responsive to ICI." (PMID 38130991, 2023). "We found that tumor-specific CD8+ TILs produced more IFNγ; blood-derived tumor-specific CD8+ T cells produced more TNF and IL-2 after restimulation with PMA and ionomycin and contained more poly-functional (IFNγ/TNF/IL-2-coexpressing) cells." (PMID 37045833, 2023).
tumor (continued). "Stimulated T cells cocultured with tumor cells showed increased TNFα and IFNγ expression on both cell types, whereas recombinant VISTA protein reversed the stimulation effect, and reduced TNFα and IFNγ expression on both cell populations." (PMID 37190254, 2023). "CRS develops in patients if T cell and tumor cell interactions lead to the release of a massive number of cytokines, such as interferon-gamma (INF-γ), TNF-α, IL-6, IL-10, and IL-15." (PMID 37443804, 2023). "The fact that tumors grow progressively upon cessation of virotherapy and the fact that tumor cell loss of IFN sensing is inadequate to prevent establishment of equilibrium support the hypothesis that immune equilibrium can occur by means other than IFNγ-induced tumor cell quiescence." (PMID 36881506, 2023). "Subsequent functional characterization documented strong induction of T cell activation, degranulation and secretion of the “antitumor cytokines” like IFNγ and IL-2 as well as potent induction of tumor cell lysis." (PMID 37122707, 2023). "Because acidic condition enhances the release of drugs by CREKA-lipo nanoparticles 8, 31, when CREKA-lipo-anti-IFNγ was delivered into the tumour, the tumour acidic environment will elicit the local release of anti-IFNγ antibodies by the nanoparticles." (PMID 37056922, 2023). "Tumor-associated astrocytes in the GBM TME are anti-inflammatory and are enriched in gene sets associated with JAK/STAT pathway activation and IFNα and IFNγ responses." (PMID 37304294, 2023). "These cytokines have antitumor effects through the activation of cytotoxic T cells, the production of interferon-gamma and the induction of apoptosis in tumor cells." (PMID 36670786, 2023). "CTLA-4 blockade also increases IFNγ and Cxcl9 expression in immunogenic tumor cells, which are crucial in type 1 immunity and vessel normalization as well as T cell recruitment." (PMID 37587450, 2023). "Tumor response to the IFNG difference between cluster 1 and cluster 2 samples was identified, and it was also predicted as one possible reason that contributes to GBM malignancy." (PMID 37122693, 2023). "In contrast, the low-TMEindex group was predominantly enriched for anti-tumor immune response processes such as inflammatory response and IFNγ response." (PMID 37055822, 2023). "IFNγ was critically important and played redundant roles in host and tumor cells such that IFNγ sensing in either compartment was sufficient for immune equilibrium." (PMID 36881506, 2023). "In mouse models, blockade of TIGIT restored NK cell cytotoxicity, increased IFNγ and TNFα expression, and promoted tumor-specific T cell immunity." (PMID 37345049, 2023). "The overexpression of PD-L1 on tumor cells is induced by genetic alterations (innate expression) and stimulation by interferon gamma (IFN-γ) released from effector T cells, including CD8+ T cells (acquired expression)." (PMID 37261359, 2023). "IFNγ is believed to be a central mediator of anti-tumour immunity 20; however, many studies have demonstrated controversial roles of IFNγ in tumour progression." (PMID 37056922, 2023). "Naïve Th cells that are activated develop into Th1 cells that hamper tumor progression through the production of interleukin (IL)-2 and interferon-gamma (IFN-γ), which increases the phagocytosis of tumor cells and the antitumor immune response." (PMID 36836712, 2023). "In the context of cancer, autophagy inhibition is reported to enhance immune cell tumor infiltration by increasing the secretion of pro-inflammatory IFNγ and C–C motif ligand (CCL)-5 (alias RANTES) and CXCL10 chemokine in melanoma, CRC and GBM murine models." (PMID 38071322, 2023). "From the results of the analysis of gene expression in the tumor, Ifnγ and Gzmb were elevated in the combination group, suggesting that CTLs were activated in the tumor." (PMID 36793737, 2023).